TTN (titin)
Diseases named in the same sentence as TTN in open-access papers (continued):
Sharing a sentence is not in itself a finding about the gene and the disease.
heart failure (continued). "We first hypothesized that p300 was the central factor leading to the reduction of α-MHC K1897 lactylation during heart failure, and p300 activator may restore the decreased α-MHC K1897 lactylation and α-MHC–Titin interaction during heart failure." (PMID 37443257, 2023). "Interestingly, the flexible PEVK domains of titin when hyperphosphorylated leads to protein stiffening, contributing to heart failure due to myofilament stiffening." (PMID 36587764, 2023). "Therefore, α-MHC K1897 lactylation and α-MHC–Titin interaction cannot be significantly rescued during heart failure by inhibiting SIRT1." (PMID 37443257, 2023). "Concurrently, SIRT1 inhibition may rescue the reduction in α-MHC K1897 lactylation and α-MHC binding to Titin during heart failure." (PMID 37443257, 2023). "Elevated myocardial diastolic stiffness as characteristically observed in heart failure, especially in heart failure with preserved ejection fraction, results from both increased myocardial collagen content and impaired titin-based cardiomyocyte distensibility." (PMID 37227779, 2023). "In heart failure patients, increased IR of essential cardiac constituents such as Titin, is hypothesized to be involved in the cellular stress response, which would be consistent with our observations." (PMID 35937994, 2022). "In heart failure, severe deviations in the composition of titin isoforms may occur due to altered splicing behaviour." (PMID 35846001, 2022). "Whilst QKI-5 overexpression significantly attenuated heart failure through regulating the expression of specific circular RNAs derived from the from the Titin (Ttn ), Formin homology 2 domain containing 3 (Fhod3 ) and Striatin/calmodulin-binding protein 3 (Strn3 ) genes." (PMID 36010571, 2022). "Titin encodes an elastic protein in cardiac muscle cells, which contributes to ventricular wall stiffness and Titin mis-splicing, which as a consequence of reduced RBM20 expression or function, is associated with heart failure." (PMID 34680108, 2021). "Conversely, both PKGI activity and titin phosphorylation at the PKGI-specific site Ser4099 (corresponding to Ser4080 in murine titin) were markedly reduced in tissue from patients with heart failure, while passive myocyte stiffness was enhanced as compared with donor hearts." (PMID 33055420, 2020). "We will describe post-translational modifications of titin that occur with heart failure." (PMID 32859027, 2020). "Post-translational modifications of titin including phosphorylation and dephosphorylation of specific elements contribute to development of heart failure and represent targets for therapies to treat heart failure." (PMID 32859027, 2020). "Heart failure is often accompanied by titin-dependent myocardial stiffness." (PMID 33055420, 2020). "These alterations may also become pathologic in heart failure where alterations in TTN phosphorylation may lead to worsening of passive and active forces reducing the ability of the heart to function normally." (PMID 31849696, 2019). "Which changes in titin phosphorylation occur in what type of human heart failure?" (PMID 30989819, 2019). "In addition to titin, RBM20 can also regulate splicing of 30 more genes in the heart that are associated with the development of heart failure." (PMID 31614708, 2019). "Which changes in titin phosphorylation occur in which animal models of heart failure?" (PMID 30989819, 2019). "We include how titin phosphorylation correlates with titin‐based stiffness in heart failure." (PMID 30989819, 2019). "The same group has proposed that regulating titin splicing, by means of modulating Rbm20 levels, could be beneficial for the heart in the setting of heart failure with preserved ejection fraction (HFpEF)." (PMID 30051286, 2018).
heart failure (continued). "The alterations in titin phosphorylation observed in heart failure could thus have a beneficial effect on systolic pump function, perhaps acting as a compensatory mechanism that helps mobilize the contractile reserve of the failing heart." (PMID 28510118, 2017). "Rare variant analysis in these regions uncovered two genes related to heart failure, TTN (P = 5.5 × 10-2) and HSD3B1 (P = 3.9 × 10-2) and one gene with unknown cardiac function FCRL2 (P = 2.8 × 10-4)." (PMID 27877193, 2016). "However, upregulation of lactate concentration through the administration of sodium lactate or inhibition of key lactate transporters in cardiomyocytes can promote the lactylation of α-MHC K1897 and the interaction between α-MHC and Titin, thereby alleviating heart failure." (PMID 40584617, 2025). "In heart failure and cardiomyopathy, RBPMS cooperates with RBM20 to regulate splicing of sarcomeric genes such as TTN, safeguarding contractile integrity, while DDX5 maintains calcium homeostasis through CAMK2D splicing, and loss of QKI results in profound sarcomere disarray and heart failure." (PMID 41399527, 2025). "Therefore, transcriptional modification of titin to preference the shorter, stiffer N2B isoform may improve systolic heart failure." (PMID 32859027, 2020). "Multiple environmental and genetic factors contribute to heart failure including age, sex, diabetes, kidney disease, inflammation, and mutations in sarcomeric proteins such as titin or cardiac splice factors such as the RNA binding motif 20 (RBM20) that regulates titin-based stiffness." (PMID 27889803, 2016). "Furthermore, low protein kinase G activity favors muscle fiber hypertrophy development and increases resting tension because of hypophosphorylation of titin, and both stiff cardiomyocytes and interstitial fibrosis contribute to the development of high diastolic LV stiffness and heart failure." (PMID 26242308, 2015). "An interesting treatment option in heart failure associated with elevated diastolic stiffness may arise from the fact that oxidative stress modulates the NO-cGMP-PKG pathway, an important modifier of titin-based stiffness." (PMID 25373878, 2015). "In patients with heart failure with preserved ejection fraction (HFpEF), a pronounced increase in passive myocardial stiffness is observed, which depends on collagen and titin, underscoring the pivotal role of ECM homeostasis in cardiac failure progression." (PMID 39849659, 2025). "The main finding of this study is that α-MHC K1897 lactylation regulates the interaction between α-MHC and Titin, and that decreasing α-MHC K1897 lactylation aggravates heart failure." (PMID 37443257, 2023). "In summary, our mini review has illustrated a promising way to attenuate myocardial stiffness characterized in heart failure, which mainly depends on the role of splicing factor RBM20 on titin pre-mRNA to modulate titin isoforms ratio." (PMID 35783855, 2022). "Integrating the results of the TBX5-targeted genes and the DEGs in toxicity pathways, we found that the dysregulation of TBX5-targeted genes, TNNT2, NPPA, TTN, ATP2A2, DES and SCN5A, contributed to the development of heart failure and arrhythmia." (PMID 32423033, 2020). "Future research will need to translate this knowledge toward novel therapeutic approaches that can modulate titin transcriptional and post-translational defects to treat DCM and heart failure." (PMID 31849696, 2019). "Diastolic dysfunction is an important contributor to the pathophysiology of heart failure, and our recent identification of RBM20 as a titin splice factor has provided a unique target to adjust the diastolic properties of the heart." (PMID 27889803, 2016). "A (diastolic) heart failure patient may well benefit from the use of NO donors, inhibitors of cGMP-degrading enzymes, antioxidants, or other drugs that block the oxidative-stress effects on titin stiffness, in that cardiomyocyte stiffness will be reduced and myocardial diastolic function improved." (PMID 25373878, 2015).
heart failure (continued). "This should enable us to dissect pathways involved in TTN-based DCM and to develop novel therapeutic strategies to combat heart failure." (PMID 26504781, 2015). "The study found a significant decrease in lactate levels in the heart tissue of the heart failure mice, which further led to a marked reduction in the lactylation modification level of α‐MHC K1897 and the interaction between α‐MHC and Titin, thereby promoting heart failure in the mice." (PMID 40443721, 2025). "In a mouse model of heart failure with preserved ejection fraction, administration of metformin, used in patients to treat type 2 diabetes, improved diastolic function based on the phosphorylation of a PKA site on N2B domain of titin." (PMID 34745372, 2021). "Due to the critical role of titin in the sarcomere and cardiomyocyte, modifications and changes to titin are seen in many forms of heart failure regardless of the etiology." (PMID 32859027, 2020). "Notably, our analysis identified RBM24 as a splice factor that determined the splicing switch of a subset of genes in the sacomeric Z-disc complex, including Titin, the major disease gene of DCM and heart failure." (PMID 30267374, 2019). "Thus, administration of sodium lactate (NALA) or inhibition of lactate efflux could treat mice with heart failure through restoring α-MHC K1897 lactylation and α-MHC–Titin interaction." (PMID 37443257, 2023).
thymoma (54 papers, 1992 to 2025). A neoplasm arising from the epithelial cells of the thymus. "Through separate association analyses of antibodies and complications, titin+, AChR+, and RyR+ cases more likely had thymoma, which is consistent with a previous report." (PMID 39968461, 2025). "The presence of anti-titin antibodies raised concerns about thymoma or thymic hyperplasia associated with MG, but a computed tomography (CT) scan of the thorax ruled them out." (PMID 40062097, 2025). "In particular, the presence of anti-titin antibodies should raise the index of suspicion as their detection is highly specific for thymoma-associated myasthenia gravis." (PMID 39574984, 2024). "The most implicated antibody in the pathogenesis of MG is the anti-AChR antibody; however, the majority of paraneoplastic thymoma-associated MG cases also have anti-titin or anti-RyR antibodies." (PMID 36919063, 2023). "Titin Abs are detected in 20 to 40% of anti-AChR-Ab-positive patients and are tightly linked to thymoma-associated MG." (PMID 37887300, 2023). "Anti-titin antibodies are detected in 68–95% of patients with thymoma-associated MG and are common in late-onset (> 60 years) non-thymoma MG patients." (PMID 36800019, 2023). "Myoid cells and TECs also express other muscle antigens, including RYR1 and TTN, which are two autoantigens in thymoma-associated MG." (PMID 36979710, 2023). "In conclusion, our results showed that the presence of anti-titin antibody has an association with more frequent hospital utilization in patients with thymoma-associated MG." (PMID 36277908, 2022). "Our results suggest that the patients with thymoma-associated MG having anti-titin antibody are more likely to experience more frequent hospitalization or ER visit to control MG than those without anti-titin antibody." (PMID 36277908, 2022). "Anti-titin antibodies are antistriational antibodies associated with thymoma-associated myasthenia gravis (MG)." (PMID 36277908, 2022). "Although its association with thymoma is well established, controversy remains in the association between the presence of anti-titin antibody and the severity of MG." (PMID 36277908, 2022). "The present study revealed that the patients with thymoma-associated MG having anti-titin antibody were more likely to be hospitalized or visit ER to manage MG." (PMID 36277908, 2022). "A total of 64 patients with thymoma-associated MG who underwent the serological test for anti-titin antibody were identified during the study period." (PMID 36277908, 2022). "Patients with thymoma-associated MG who conducted the serological test for anti-titin antibody were retrospectively included." (PMID 36277908, 2022). "Comparison of demographic and clinical features in patients with thymoma-associated MG between the titin+ and titin– groups." (PMID 36277908, 2022). "A possible reason for this incongruity is that most of our DSP-MG patients (11/17) were also positive for ryanodine receptor and titin antibodies, which occurs at a high frequency in thymoma-associated MG." (PMID 33438140, 2021). "As titin Abs are frequently detected in non‐thymoma LOMG, this finding indirectly supports the association between DR7 and this MG subtype, possibly not detected in their study because of the low cut‐off age (40 years)." (PMID 33547763, 2021). "It is well‐known that LOMG is associated, in about 50% of the cases, with Abs to titin and, to a lesser extent, to the ryanodine receptor (RyR), which are otherwise markers of thymoma." (PMID 33547763, 2021). "MG patients with myositis and/or myocarditis as well as late-onset and thymoma-associated MG had anti-titin, anti-ryanodine receptor, and anti-Kv1.4 antibodies." (PMID 30918333, 2019). "We predicted that thymoma-associated antibodies (titin-Ab, SMA-Ab, and CAE-Ab) and anti-M7 antibodies play an important role in the concurrent presence of MG and myositis and myocarditis." (PMID 31379720, 2019).
thymoma (continued). "Titin-Ab and RyR-Ab are determined by enzyme-linked immunosorbent assay or immunoblot, and have been recently detected in first cases of thymoma-MG with co-manifesting myositis." (PMID 27623618, 2016). "This is postulated because of the presence of titin and another autoantibody to the RyR channel of the sarcoplasmic reticulum in patients with thymoma, which is associated to an increase of the severity of myasthenia gravis." (PMID 27445963, 2016). "The presence of titin and RyR antibodies is associated with more severe disease in thymoma MG and in late-onset MG." (PMID 21860784, 2011). "Similar to thymoma-associated MG, the presence of titin antibodies in irMG may predict worse outcomes and higher fatality." (PMID 40062097, 2025). "Moreover, previous studies have shown that, out of the three anti-striational antibodies, anti-titin and anti-Kv 1.4 can be used as biomarkers for myocarditis and/or myositis in patients with MG, especially for late-onset and thymoma-associated cases." (PMID 38673546, 2024). "Titin Abs are related to thymoma-associated MG and more frequent hospitalization." (PMID 37887300, 2023). "The presence of anti-titin antibody could be utilized in predicting treatment response in patients with thymoma-associated MG." (PMID 36277908, 2022). "Personalized explanation and careful monitoring strategy could be required in patients with thymoma-associated MG with anti-titin antibody for the timely detection of relapses." (PMID 36277908, 2022). "Therefore, the serological test for anti-titin antibody can be used as a clinical indicator when treating patients with thymoma-associated MG." (PMID 36277908, 2022). "Similar to titin, RyRAbs are also associated with late onset MG and thymoma." (PMID 33362698, 2020). "TitinAbs are detected in around 20–40% AChRAb positive MG patients, with associated symptoms of late onset MG and thymoma-associated MG, therefore the presence of titin Abs in early onset MG patients could be a biomarker for thymoma." (PMID 33362698, 2020). "Considering that titin-Ab and RyR-Ab have been mostly associated with invasive/malignant types of thymoma, in the presence of such antibodies in MG or GrM-MG patients, the employment of a thymectomy technique that assures complete resection is decisive for the prognosis." (PMID 27623618, 2016). "These antibodies react with epitopes on the muscle proteins titin and ryanodine receptor, are found mainly in association with thymoma and late-onset myasthenia gravis, and may correlate with myasthenia gravis severity." (PMID 23193443, 2012). "Thus, careful assessment and monitoring strategy could be required in patients with thymoma-associated MG with anti-titin antibody to manage frequent relapses." (PMID 36277908, 2022). "Additional evidence by future larger studies is warranted to investigate whether titin-Ab and RyR-Ab are frequently detected among MG-myositis patients, and whether the presence of these antibodies may suggest an underlying thymoma in the MG-myositis patient group." (PMID 27623618, 2016). "Titin and ryanodine receptor (RyR) antibodies are found in 95% of thymoma MG and 50% of late-onset MG (MG onset ≥50 years), are associated with severe disease, and may predict thymoma MG outcome." (PMID 21860784, 2011). "Clinical studies have shown that titin antibody testing has a sensitivity of 69% and a specificity of 97% for thymic epithelial tumors, and Titin-Ab are detectable in approximately 70 to 90% of MG patients with thymoma." (PMID 41393996, 2025). "Specifically, anti-titin antibodies have been identified as a sensitive marker of severe MG and thymomas." (PMID 40062097, 2025). "On the other hand, anti-striated muscle Abs (e.g., titin Abs) can be found in patients with thymoma-related MG." (PMID 40181971, 2025).